APOB (apolipoprotein B)
Diseases named in the same sentence as APOB in open-access papers (continued):
Sharing a sentence is not in itself a finding about the gene and the disease.
dyslipidemia (continued). "In addition, another commonly studied polymorphism is found in the APOB gene in exon 29 (rs1042031) involves a silent mutation from cytosine to thymine in the third base of codon 2488 and has been reported to be associated with dyslipidemia." (PMID 25292352, 2014). "Inappropriate storage of fatty acids as triglycerides in adipocytes and their removal from adipocytes through lipolysis and subsequent oxidation may cause the atherogenic dyslipidemia phenotype of elevated apolipoprotein B levels and subsequent hypertriglyceridemia." (PMID 23316323, 2012). "Low-density lipoprotein cholesterol (LDL-C) has now been the primary target for lipid-lowering therapy in the European and US guidelines for the management of dyslipidemia, with increasing interest in apolipoprotein B (ApoB) as a secondary target." (PMID 41030852, 2025). "Further prospective studies are needed to validate these findings and assess apoB’s role in clinical guidelines for CAD risk prediction, dyslipidemia diagnosis, and preventive strategies." (PMID 40852379, 2025). "Further studies are needed in larger cohorts to test the feasibility of ACVD screening and to understand the natural history of apoB-dyslipidemia, ACVD and cardiac dysfunction in young women." (PMID 40995592, 2025). "Dyslipidemia in HF should continue to be managed according to ApoB-driven, guideline-directed lipid-lowering strategies, including statins and ezetimibe when indicated, while maintaining SGLT2 inhibitors for their established cardiorenal benefit." (PMID 41567901, 2025). "In T2DM, ApoB levels are frequently elevated due to insulin resistance-driven dyslipidemia characterized by triglyceride-rich VLDL, small dense LDL, and reduced HDL-C." (PMID 41346943, 2025). "Metabolites like glycoprotein acetyls, the Apolipoprotein B/Apolipoprotein A-1 ratio, and lactate have emerged as potential biomarkers for insulin resistance and metabolic syndrome, highlighting their potential value in clinical applications." (PMID 40507103, 2025). "Individuals in the high‐VAT group exhibited systemic metabolic disturbances, with significantly elevated conventional CVD risk markers including WC, BMI, TG, and ApoB, consistent with VAT's established role as a core component of metabolic syndrome." (PMID 40825749, 2025). "The ARCHES-2 (Study of ARO-ANG3 in Adults with Mixed Dyslipidemia) phase II b study demonstrated that ARO-ANG3 significantly decreased ANGPTL3 expression and atherogenic triglyceride-rich lipoproteins, LDL-C and total apoB, in patients with mixed dyslipidemia." (PMID 38592091, 2024). "Its primary elements include dyslipidemia, marked by elevated triglycerides (TG) and apolipoprotein B (apoB)-containing lipoproteins, and low levels of high-density lipoproteins (HDLs)." (PMID 39391415, 2024). "Furthermore, increasing LAP values have been associated with atherogenic dyslipidemia (increased apoB levels, reduced LDL and HDL particle size) and insulin resistance, which in turn could lead to arterial stiffness and possibly coronary atherosclerosis progression." (PMID 39452286, 2024). "Further investigation using these strains will likely reveal additional organs that pathologically respond to APOB lipoprotein-mediated dyslipidemia." (PMID 39196121, 2024). "In selecting a candidate proband inside a family showing a cluster of CV risks, including metabolic syndrome pattern, the consideration to check for ApoB level should be beneficial." (PMID 38392258, 2024). "Particularly noteworthy is the identification of a connection between these SNPs and arterial fibrillation along with indicators of dyslipidemia (triglyceride-to-HDL ratio, serum ApoB),—significant risk factors for IS." (PMID 39337941, 2024). "Second, through use of the mCherry-APOB reporter mouse, KCs were shown to recognize APOB lipoproteins in the context of atherogenic dyslipidemia." (PMID 39196121, 2024).
dyslipidemia (continued). "The concordance in dyslipidemia classification between traditional lipid tests and ApoB at cutoffs of 145 mg/dL, 130 mg/dL, and 100 mg/dL was 78.4%, 81.3%, and 74.7%, respectively." (PMID 38535329, 2024). "Serum analysis has been considered in children since the 1990s, formerly as a candidate marker to screen for FH affected subjects, then to distinguish other dyslipidemias in subjects carrying ApoB exceeding 100 mg/dL levels." (PMID 38392258, 2024). "Future research should delve into the clinical implications of different ApoB cutoffs, emphasizing the need for comprehensive clinical data on dyslipidemia and CVD, along with assay standardization." (PMID 38535329, 2024). "Dyslipidemia prevalence has been reported to be between 19–25% in US adolescents when defined as any abnormal lipid or apolipoprotein B." (PMID 39339743, 2024). "The prevalence of dyslipidemia identified using either traditional lipid tests or ApoB in this study (44.9%) was more aligned with the KNHANES findings." (PMID 38535329, 2024). "In this study, the overall percentage agreement between dyslipidemia identified through traditional lipid tests and the high risk of CVD determined by ApoB results, using various cutoffs, was highest with ApoB ≥ 130 mg/dL." (PMID 38535329, 2024). "We determined the prevalence of dyslipidemia based on both traditional lipid tests and ApoB test results." (PMID 38535329, 2024). "As previously discussed, quercetin significantly improves dyslipidemia in diabetic rats, including reductions in the apolipoprotein B (ApoB)/A1 ratio, total cholesterol, triglycerides, and LDL-to-HDL ratios." (PMID 39795285, 2024). "While ApoB has been extensively studied in Europeans, its importance has been relatively less emphasized in Korea, and Korean guidelines for dyslipidemia suggest ApoB evaluation in patients with diabetes and familial hypercholesterolemia." (PMID 37375689, 2023). "The established reference intervals were compared with previous ApoB results from the literature and current international guidelines for dyslipidemia." (PMID 37892015, 2023). "Other lipid markers, such as low-density lipoprotein (LDL) cholesterol, triglycerides, and apolipoprotein B (Apo-B), are also important in the diagnosis and management of dyslipidemia." (PMID 37049565, 2023). "One of the primary risk factors for CVDs is dyslipidemia, characterized by elevated total cholesterol, LDL-C, triglycerides, apolipoprotein B (ApoB), and lipoprotein A (Lp(A)), and decreased HDL-C." (PMID 37761482, 2023). "Apolipoprotein B (ApoB) is a specific lipoprotein composition of serum lipids and has not received much attention in the previous studies on the relation of dyslipidemia and CKD compared with the traditional lipid parameters." (PMID 37124758, 2023). "The indicators for dyslipidemia in our study were elevated serum TC, LDL-C, ApoB and Lipo (a) which are some known risk factors for CVD." (PMID 37299433, 2023). "The association between serum levels of endothelial lipase (EL) and the serum levels and composition of apolipoprotein B (apoB)-containing lipoproteins in healthy subjects and patients with metabolic syndrome (MS) remained unexplored." (PMID 37445857, 2023). "It has previously been associated with metabolic syndrome and elevated serum cholesterol, LDL, and ApoB levels in individuals of African, East Asian, European, Hispanic, and South Asian ancestry." (PMID 37342358, 2023). "According to the Korean Guidelines for the Management of Dyslipidemia, ApoB measurements are recommended for diabetes patients." (PMID 37375689, 2023). "Elevated levels of apolipoprotein B are a sign of metabolic syndrome, including obesity, diabetes, and heart disease." (PMID 35657779, 2022). "We also noted unique independent effects of APOB 3′ intergenic region variants on triglyceride levels, HDL and remnant cholesterol levels, and metabolic syndrome." (PMID 36499290, 2022).
dyslipidemia (continued). "ApoB has been proposed as a better predictor of cardiovascular risk than LDLC in patients with mild-to-moderate hypertriglyceridemia, diabetes, and metabolic syndrome characterized by high numbers of small dense LDL particles." (PMID 34955672, 2022). "With the exception of the novel loci identified in our investigation, subsequent GO and KEGG pathway analyses of the remaining significant loci related to ApoA1 and ApoB/ApoA1 showed a dyslipidemia-related function." (PMID 36140721, 2022). "Dyslipidemia includes elevated levels of fatty acids, apolipoprotein B (ApoB), TG, high levels of low-density lipoproteins (LDL) and low levels of HDL, leading to an increase in CVD risk." (PMID 35329071, 2022). "Due to at least moderate LD between the lead SNPs downstream of APOB, we selected rs4665709, the lead SNP of metabolic syndrome, for analysis." (PMID 36499290, 2022). "European dyslipidemia guidelines recommend lowering the LDL-C and apolipoprotein B (apo B) levels in high-risk patients such as patients with T2D." (PMID 36324177, 2022). "In contrast, total and normalized anti-ApoB IgM, that have been suggested as anti-inflammatory, were significantly lower in diabetic patients (p = 0.012) and in patients with the metabolic syndrome (p = 0.005)." (PMID 35479271, 2022). "Studies have demonstrated that ApoB has a certain correlation with metabolic syndrome and insulin resistance." (PMID 35433838, 2022). "ApoB has been related to dyslipidemia processes and it is considered a significant predictor of cardiovascular diseases such as myocardial infarction." (PMID 34829826, 2021). "The GLM showed a significant association between OB classified by BMI with each of the following lipid markers: high TG, low HDL, low ApoA, high ApoB, and dyslipidemia." (PMID 34886385, 2021). "In this regard, dyslipidemia, i.e., Apolipoprotein B, appears to unambiguously contribute to a more accurate CVD risk prediction and evaluation." (PMID 34066182, 2021). "Among ethnicities, BMI performed better at predicting most of the lipid markers (low HDL 0.95, CI: 0.90–1.00; high TG 0.82, CI: 0.73–0.93; high ApoB 0.77, CI: 0.61–0.94; dyslipidemia 0.76, CI: 0.64–0.97) in NM-Seris." (PMID 34886385, 2021). "In contrast, HDL-C and ApoA1 levels and ApoA1/ApoB ratio were significantly lower in the dyslipidemia group than in the normal group (P < 0.001)." (PMID 33612478, 2021). "The apoB/apoA-1 ratio is more strongly related to CV risks than apoB in persons with pre-diabetes and metabolic syndrome often characterised by hypertriglyceridaemia." (PMID 34851955, 2021). "The diagnosis of this dyslipidemia is suggested by a fluctuating lipid profile, apolipoprotein B (apo B) levels >90th population percentile for age and gender and a first-degree family history of premature cardiovascular disease." (PMID 33588820, 2021). "FCHL is characterized by three phenotypes; isolated hypercholesterolemia, mixed dyslipidemia and isolated hypertriglyceridemia, and particularly is accompanied by elevated apolipoprotein B (Apo B) levels." (PMID 33952259, 2021). "It contributes to dyslipidemia via the expression of microsomal triglyceride transfer proteins that help in the assembly of apolipoprotein B in the liver." (PMID 32047529, 2020). "Among these potential candidate genes, there are six genes (CETP, APOB, TMEM258, FADS2, FADS1, and PVRL2) associated with all phenotypes of dyslipidemia." (PMID 32425817, 2020). "In this study, we constructed GRSs composed 7 genetic variants (ANGPTL3 rs10889353, APOB rs7557067, GCKR rs780092, C2orf16 rs1919127, TRIB1 rs2954029, FADS1-FADS2-FADS3 rs174547, and APOA5 rs2266788) associated with dyslipidemia using GWAS studies." (PMID 33339179, 2020).
dyslipidemia (continued). "ApoB is closely related to the expression of the metabolic syndrome (MetS), a worldwide increasingly prevalent phenotype highly influenced by life habits." (PMID 32430061, 2020). "Some studies used different definitions of metabolic syndrome, such as biomarkers including high-sensitivity C-reactive protein or apolipoprotein B, whereas some defined the condition by diagnosis or treatment for hypertension, dyslipidemia, or diabetes." (PMID 31443279, 2019). "Atherogenic dyslipidemia of 3.4% in our patients signifies an increase in apolipoprotein B (ApoB), and a shift of LDL pool towards small, dense LDL that are cholesterol-ester depleted, and more atherogenic with higher risk for ASCVD." (PMID 33708292, 2019). "In general, obesity causes abnormalities in lipoprotein metabolism such as dyslipidemia and hyperlipidemia by increasing the synthesis of VLDL, LDL, ApoB, and total body cholesterol." (PMID 30463250, 2018). "Especially in MetS, these patients commonly had elevated ApoB levels, smaller LDL particle size, and elevated ApoCIII levels and as such metabolic syndrome is associated with residual CVD risk." (PMID 29785308, 2018). "Common cardiovascular disease (CVD) RFs namely hypertension (HTN), diabetes mellitus, dyslipidemia, abdominal obesity, smoking, low apolipoproteins A ( apo-A) and high apolipoprotein B (apo-B) were evaluated." (PMID 29118949, 2017). "For dyslipidemia, we observed associations with BAD (FDR 0.02) and Apolipoprotein B (APOB) (FDR 0.11)." (PMID 29126409, 2017). "Other groups showed that the combination of suppression of apoB expression and enhanced de novo lipogenesis, which happens under insulin resistance or metabolic syndrome conditions, induced enlargement of VLDL particles in circulation." (PMID 28792970, 2017). "The haplotype of rs2483058C-rs2580520G was associated with an increased risk of dyslipidemia (OR: 1.44, 95% CI: 1.17–1.78, P < 0.001), it showed consistent association with serum TC, HDL-C, ApoA1 and the ratio of ApoA1 to ApoB." (PMID 28912560, 2017). "Common variants in OGFOD3 and APOB as well as rare and common BAD variants were significantly (p<0.05) associated with dyslipidemia." (PMID 29126409, 2017). "In this study, VLDL‐TG production was not significantly different between measured time points, suggesting that the differences observed in dyslipidemia are likely due to differences in the clearance of apoB‐lipoproteins." (PMID 29038350, 2017). "The intake of HFD causes the appearance of typical dyslipidemia characterized by increased content of free fatty acid and triglycerides and, often, increased LDL-C and ApoB with decreased HDL-C." (PMID 28661434, 2017). "It includes dyslipidemia elevated triglycerides and apolipoprotein B (apoB), containing lipoproteins and low high-density lipoproteins (HDL), as well as elevated arterial blood pressure (BP) and dysregulated glucose homeostasis." (PMID 27006707, 2016). "In the present study, apigenin markedly decreased plasma total-cholesterol levels, as well as plasma apoB levels and the apoB/apoA1 ratio, indicating its protective role against atherogenic dyslipidemia in HFD-induced obese mice." (PMID 27213439, 2016). "Dyslipidemia is characterized by lipids disturbance including an elevation of lipoproteins containing apolipoprotein B (apoB), elevated TGs, increased levels of small particles of LDL, and low levels of HDL- cholesterol." (PMID 26198245, 2015). "The superiority of apoB against LDL-C as a CVD risk biomarker is more intense in populations which are characterized by insulin resistance and metabolic syndrome features." (PMID 26370413, 2015). "Hypothyroidism is one of the most common causes of secondary dyslipidemias which results from reduced LDL clearance and therefore raised levels of LDL and apoB." (PMID 25300222, 2014).
dyslipidemia (continued). "In Henry S Kahn's study, enlarged waist with elevated triacylglycerols alone identified more persons with greater concentrations of LDL cholesterol and apolipoprotein B than did metabolic syndrome alone." (PMID 24663403, 2014). "In recent large Asian studies, apoB was a strong predictor of the metabolic syndrome and was proven to be reliably estimated by routine lipid biochemistry." (PMID 23536999, 2013). "Treatment with curcumin significantly lowered glucose, Tg, cholesterol, LDL, APO1A and APOB levels, indicating that curcumin is a good compound to treat metabolic syndrome." (PMID 23533564, 2013). "The most advanced oligonucleotide antisense for the treatment of dyslipidemia is mipomersen, an apoB synthesis inhibitor." (PMID 24278757, 2012). "The new equation we developed to estimate serum apoB concentrations is accurate and can be used in diverse subgroups of patients including those with diabetes, atherogenic dyslipidemia, and those taking lipid-lowering agents." (PMID 23284722, 2012). "The 2009 Canadian dyslipidemia guidelines recommend Apolipoprotein B as the primary alternate target to LDL-C." (PMID 23304534, 2012). "In model 2, for patients with diabetes and atherogenic dyslipidemia, apoB levels were slightly over-estimated, as the estimated apoB was more than 150 mg/dl, whereas apoB levels were under-estimated in patients taking lipid-lowering agents." (PMID 23284722, 2012). "It consists of an atherogenic dyslipidemia ((i.e., elevated triglycerides and apolipoprotein B (apo-B) and low high-density lipoprotein cholesterol (HDL-C)), elevation of blood pressure and glucose, prothrombotic and proinflammatory states." (PMID 21687582, 2011). "Atherogenic dyslipidemia consists of an aggregation of lipoprotein abnormalities including elevated serum triglyceride and apolipoprotein B (apoB), increased small LDL particles, and a reduced level of HDL cholesterol (HDL-C)." (PMID 21359028, 2010). "Elevated body weight, waist circumference, and low HDL-C levels have been found to be more common contributors to metabolic syndrome in women, while blood pressure and apolipoprotein B have been found to be more common contributors in men." (PMID 19781089, 2009). "Increases in BF% and WHR are associated with dyslipidemia, including increased plasma TG, NEFA and apoB." (PMID 16606459, 2006). "In addition, the degree of LDL-C and ApoB lowering achieved with both compounds was less than that observed with evinacumab in patients with severe hypertriglyceridemia or mixed dyslipidemia despite dramatic reductions in circulating ANGPTL3 levels." (PMID 40640392, 2025). "We did not include apoB in this example as it is not yet measured in routine clinical practice, but including apoB would convert the system from a dyslipidemia into a dyslipoproteinemia classification system, which would likely be beneficial, especially for risk stratification." (PMID 41226954, 2025). "Western diets, which are rich in saturated fats and low in fiber, can lead to broader dyslipidemia but may affect different lipid subtypes (e.g., apoB and sdLDL)." (PMID 40731919, 2025). "Apolipoprotein B (ApoB) is essential for the assembly and secretion of triglyceride (TG)-rich VLDL particles, and its dysfunction is linked to metabolic disorders, including dyslipidemia and liver steatosis." (PMID 40180213, 2025). "Moreover, previous studies have shown that apolipoprotein B (Apo-B) partially mediates the relationship between SOA and the risk of metabolic syndrome." (PMID 40395814, 2025). "Our pilot results supports the potential of apoB-dyslipidemia, cIMT, carotid plaque height and left ventricular diastolic dysfunction and remodeling to be used in screening for CVD risk in high-risk populations such as overweight-obese women with and without PCOS." (PMID 40995592, 2025).